KRAS (KRas proto-oncogene, GTPase)
Diseases named in the same sentence as KRAS in open-access papers (continued):
Sharing a sentence is not in itself a finding about the gene and the disease.
non-small cell lung carcinoma (continued). "However, Cdkn2a inactivation increased tumor number in the KRAS G12D context more than in KRAS G12C, consistent with genomic analyses of human non-small cell lung cancers describing enrichment of CDKN2A mutations in tumor with KRAS G12D relative to KRAS G12C or other KRAS variants." (PMID 37828026, 2023). "Finally, a few KRAS inhibitors are in ongoing clinical trials, including adagrasib (formerly MRTX849), due to the discovery of FDA-approved sotorasib, which was the breakthrough advance in developing targeted therapy for patients with non-small cell lung cancer and KRAS mutations." (PMID 35408658, 2022). "Activating KRAS mutations occur in about 30% of pulmonary adenocarcinoma (AC) cases and the discovery of specific inhibitors of G12C-mutated KRAS has considerably improved the prognosis for a subgroup of about 14% of non-small cell lung cancer (NSCLC) patients." (PMID 35888776, 2022). "Non-small cell lung carcinoma (NSCLC), the leading cause of cancer mortality worldwide, has known driver mutations of nodes on this pathway in ~75% of cases, including: ~30% KRAS, ~11% EGFR, ~7% BRAF and ~11% NF1 mutations." (PMID 31182717, 2019). "Though T790M gatekeeper mutations in EGFR and KRAS mutations define resistance in a majority of non-small cell lung carcinoma (NSCLC) and colorectal cancer patients respectively, these mutations contribute minimally to resistance in HNSCC patients." (PMID 31827134, 2019). "Direct deoxy ribonucleic acid (DNA) sequencing of the KRAS gene allows for the detection of novel KRAS mutations, and it might be advocated in patients with advanced non-small cell lung cancer in view of the emerging role of KRAS as a potential therapeutic target." (PMID 26284123, 2015). "We sequenced the KRAS gene and investigated the associations of variations in 108 patients with non-small cell lung carcinoma (NSCLC), the most common form of LC, and in 116 patients with CRC." (PMID 25158139, 2014). "Clinical implications of KRAS mutations in advanced non-small cell lung cancer remain unclear." (PMID 23724098, 2013). "However, in our analysis of the exonic regions encoding the first 100 amino acids of KRAS in 110 surgically resected early-stage non-small-cell lung cancers, we have found 18 mutations, and all were in either codon 12 or codon 13, encoded by exon 2 (W. Pao, R. Wilson, H. Varmus, unpublished data)." (PMID 15696205, 2005). "For instance, combining FAK and ERK5 inhibitors has led to improved antitumor responses and reduced resistance in KRAS mutant non-small cell lung cancer (NSCLC)." (PMID 39976799, 2025). "In conclusion, our study provides valuable insights into the interplay between PD-L1 expression, HIF-1α expression, and KRAS mutation status in non-small cell lung cancer (NSCLC), particularly in KRAS G12C mutant cases." (PMID 39996842, 2025). "For instance, USP7 promotes non-small cell lung cancer progression by deubiquitinating and stabilizing KRAS." (PMID 41488674, 2025). "KRAS mutations activate EGFR signaling pathways, which are associated with an increased risk of brain metastases in non-small cell lung cancer (NSCLC) patients." (PMID 40362343, 2025). "For example, mutations in the KRAS gene, which is crucial in the RAS/RAF/MAPK signaling pathway, are common in several cancers, such as colorectal cancer and non-small cell lung cancer (NSCLC)." (PMID 40964172, 2025). "For instance, USP7 is a key deubiquitinase that regulates RAS stability, and targeting USP7 is a promising strategy for combating KRAS inhibitor resistance in non-small cell lung cancer (NSCLC)." (PMID 40170095, 2025). "Non-small cell lung cancer (NSCLC) remains a leading cause of cancer-related mortality globally, with KRAS mutations present in approximately 20–25% of cases." (PMID 40316534, 2025).
non-small cell lung carcinoma (continued). "In short, we demonstrate that pemigatinib and KRAS G12C inhibitors are promising agents for combination therapy in non-small cell lung cancer with a mesenchymal-like phenotype harboring high FGFR1 expression and KRAS G12C mutations to broaden patient response." (PMID 40788860, 2025). "Mutations in EGFR, KRAS, and BRAF are common in non-small cell lung cancer (NSCLC), while ALK, ROS1, and RET rearrangements define distinct molecular subtypes." (PMID 41012430, 2025). "For example, trametinib showed a similar progression-free survival and response rate as docetaxel in patients with previously treated KRAS-mutant-positive non-small-cell lung cancer in a randomized phase II study." (PMID 41311737, 2025). "For example, activating EGFR mutations in non-small-cell lung cancer predict robust responses to EGFR inhibitors, whereas tumors with KRAS mutations are typically resistant." (PMID 41295218, 2025). "RASON is a promising therapeutic target for KRASG12C mutant non-small cell lung cancer either as a monotherapy or in combination with KRAS inhibitors." (PMID 40128846, 2025). "Targeted therapy has achieved significant success in the treatment of non-small cell lung cancer (NSCLC), particularly in patients harboring common oncogenic driver mutations such as EGFR, KRAS, and ALK rearrangement." (PMID 40246819, 2025). "In non-small cell lung cancer (NSCLC), molecular testing for EGFR mutations, ALK or ROS1 rearrangements, BRAF V600E mutations, and KRAS G12C mutations is now standard practice." (PMID 41010962, 2025). "In individuals with non-small cell lung cancer (NSCLC), Kirsten rat sarcoma viral oncogene (KRAS) mutations serve as crucial oncogenic drivers." (PMID 41158041, 2025). "KRAS is the most frequently mutated oncogene in human cancers, with KRASG12C being a prevalent driver mutation in 12–13% non-small cell lung cancer (NSCLC) cases." (PMID 40128846, 2025). "Selective covalent inhibitors targeting KRASG12C, such as AMG-510 (sotorasib), have also emerged to combat constitutively active KRAS, but are currently only approved as a second line treatment in patients with non-small cell lung carcinoma." (PMID 39899215, 2025). "For instance, a study demonstrated that alkaloids, such as berberine and coptisine bind to the KRAS DNA G4 in the promoter region, effectively inhibiting KRAS transcription in non-small-cell lung cancer cells (H460 and A549)." (PMID 40333779, 2025). "The KRAS G12C mutation, involving a glycine-to-cysteine substitution, is particularly significant in non-small-cell lung cancer, where it leads to persistent activation of the KRAS oncogenic pathway, driving uncontrolled cell growth." (PMID 39858030, 2025). "KRAS p.G12C inhibitors, such as sotorasib and adagrasib, have demonstrated significant clinical efficacy, especially in KRAS G12C-mutant non-small cell lung cancer." (PMID 40538856, 2025). "KRAS mutations also upregulate ME1 expression in hepatocellular carcinoma (HCC), non-small-cell lung cancer (NSCLC), and colorectal cancer (CRC)." (PMID 39996805, 2025). "The two most common and mutually exclusive driver mutations in non-small cell lung cancer affect EGFR and KRAS oncogenes." (PMID 40524071, 2025). "Compared to non-small cell lung cancer, IMA more frequently harbors KRAS mutations in the order p.G12V, p.G12D, and p.G12C." (PMID 40419662, 2025). "A meta-analysis was conducted to evaluate the association between KRAS mutation status and progression-free survival (PFS) in patients with non-small-cell lung cancer (NSCLC) receiving first-line immune checkpoint inhibitor monotherapy." (PMID 40558308, 2025). "KRAS mutations are common in non-small cell lung cancer (NSCLC) and are associated with patient prognosis; however, targeting KRAS has faced various difficulties." (PMID 39681355, 2025).
non-small cell lung carcinoma (continued). "For KRAS-mutant non-small cell lung cancer (NSCLC), a Phase II study (NCT01951690) evaluated defactinib, demonstrating improvements in progression-free survival across four cohorts." (PMID 39976799, 2025). "KRAS mutations at G12, G13, and Q61 positions are predominant and are prevalent in many cancers including pancreatic ductal adenocarcinoma (PDAC), non-small cell lung cancer (NSCLC), and colorectal adenocarcinoma (CRC), and respectively." (PMID 40756996, 2025). "For example, sotorasib and adagrasib, the inhibitors against KRAS-G12C mutant protein have been proved to have good activity in patients with non-small-cell lung cancer (NSCLC) and other solid tumors." (PMID 38475936, 2024). "Here, a proof-of-concept experiment was performed to show that BOLT-seq can be used in a large-scale screen for drug-induced perturbation of gene expression in NIC-H358 cells, which are KRAS G12C mutant non-small cell lung carcinoma cells." (PMID 38413820, 2024). "Despite the development of inhibitors targeting active GTP-bound (ON) KRAS(G12C) for the treatment of KRAS G12C-driven non-small cell lung cancer (NSCLC), resistance remains an issue." (PMID 39025835, 2024). "Recent advancements are highlighted by sotorasib, a small molecule inhibitor specifically targeting the KRAS G12C mutant protein, which is prevalent in non-small cell lung cancer (NSCLC), pancreatic cancer, and colorectal cancer." (PMID 38816668, 2024). "Metastatic non-small cell lung cancer (NSCLC) poses a significant clinical challenge, prompting a focused investigation into the role of KRAS mutations in prognosis and treatment response." (PMID 38860089, 2024). "Our results revealed unique mutation rates in the EGFR, KRAS, and ROS1 genes among non-small cell lung cancer patients." (PMID 38828424, 2024). "Another study revealed that HIF1A-As2 epigenetically activates MYC by attracting DHX9 to the MYC promoter, thereby promoting the transcription of MYC and its target genes in KRAS-driven non-small cell lung cancer." (PMID 39668816, 2024). "Despite the breakthrough of KRAS G12C inhibitors in treating non-small-cell lung cancer, other KRAS-targeted therapy still has poor clinical efficacy." (PMID 39054529, 2024). "The 11 currently reportable or actionable variants for non-small cell lung cancer (NSCLC) were extensively verified (n=126) (ALK, EGFR, BRAF, KRAS, NTRK 1/2/3, ROS, RET, MET, ERBB2)." (PMID 36522176, 2024). "Non-small cell lung cancer (NSCLC) is a leading cause of cancer-related deaths, particularly among patients with a specific mutation in the KRAS gene known as KRAS G12C." (PMID 39518114, 2024). "Sotorasib monotherapy resulted in a 37.1% objective response rate (ORR) in patients with KRAS-G12C mutant non-small cell lung cancer (NSCLC)." (PMID 38278976, 2024). "Remaining drug-tolerant persistent (DTP) cancer cells limit the efficacy of targeted therapy in EGFR, ALK and KRAS mutant non-small cell lung cancer (NSCLC)." (PMID 38702301, 2024). "We combined the data from three independent studies on KRAS G12C inhibition (G12Ci) in six non-small cell lung carcinoma (NSCLC) cell lines, normalizing within each cell line to DMSO." (PMID 38791964, 2024).
non-small cell lung carcinoma (continued). "The IDH1 and IDH2 mutations are also present in 0.9% of colorectal cancer, associated with the BRAF V600E mutation, in 0.5% of non-small cell lung carcinoma (NSCLC), co-existing with KRAS mutations and in melanoma, occurring with NRAS mutations." (PMID 39123479, 2024). "In models of KRAS G12C oncogenic-driven non-small cell lung carcinoma, orally delivered FAK inhibitors radio-sensitize tumors, synergize with inhibitors of KRAS G12C and boost checkpoint inhibitor immune responses via tumor intrinsic and extrinsic mechanisms." (PMID 39034922, 2024). "The first vaccine therapy and Sargramostim trial for non-small cell lung cancer patients was conducted in 1999, marking the beginning of immunotherapy for KRAS malignancies (NCT00005630)." (PMID 39252322, 2024). "Most existing KRAS G12C inhibitors such as Sotorasib or MRTX849 have shown remarkable efficacy in KRAS G12C driven cancers such as non-small cell lung cancer but limited effect on PDAC due to the rare occurrence of G12C mutation cases." (PMID 38892436, 2024). "In a phase 1 trial on advanced or metastatic tumors with KRAS G12C mutations, Divarasib achieved an objective response rate (ORR) of 56.4% in non-small-cell lung cancer patients and a median progression-free survival (PFS) of 13.1 months." (PMID 39770538, 2024). "Another study examined the impact of feature harmonization on radio-genomics analysis for the prediction of KRAS and EGFR mutations from non-small cell lung cancer from PET/CT images." (PMID 38575814, 2024). "Targeted inhibition of NOP56 expression combined with rapamycin treatment significantly inhibited the growth of KRAS-mutant non-small cell lung cancer." (PMID 36741964, 2023). "There are in vitro and in vivo studies being conducted with darovasertib to determine if it can be used in combination with the KRAS inhibitors, sotorasib and adagrasib, to treat non-small cell lung cancer and hepatocellular carcinoma." (PMID 37576814, 2023). "Kirsten rat sarcoma viral oncogene homolog (KRAS) is the most frequently mutated oncogene in human cancer and, in particular, in non-small cell lung cancer (NSCLC) that is associated with a poor prognosis." (PMID 38023987, 2023). "This phase II trial evaluated the safety and activity of the MEK inhibitor binimetinib combined with hydroxychloroquine in patients with advanced KRAS-mutant non-small cell lung cancer." (PMID 37186063, 2023). "Recently, two new drugs, sotorasib (Lumakras) and adagrasib (Krazati), have been approved to treat people with non-small cell lung cancer that has the KRAS G12C mutation, and those in development include MRTX1133 targeting KRAS G12D mutations." (PMID 37686149, 2023). "For example, sotorasib, a KRAS inhibitor that targets KRAS G12C mutations, was approved in 2021 by the FDA for the treatment of advanced non-small-cell lung cancer." (PMID 37242560, 2023). "Recent studies have found that the expression of NOP56 in KRAS mutant non-small cell lung cancer cell lines is significantly higher than that in KRAS wild-type non-small cell lung cancer cell lines." (PMID 36741964, 2023). "To date, the only approved direct KRAS inhibitor is Sotorasib (AMG 510) which specifically targets KRAS p.Gly12Cys in non-small-cell lung carcinoma by forming a covalent bond with the 12-cysteine." (PMID 37051535, 2023). "Pyrimidine synthesis has recently been identified as a new therapeutic target in KRAS/LKB1 mutant non-small cell lung cancer and PTEN mutant cancers." (PMID 37240659, 2023).
non-small cell lung carcinoma (continued). "The key mutation in PDAC is KRAS, which is notoriously resistant to drugs; however, KRAS inhibitors are indeed emerging, with the recent FDA approvals in non-small cell lung cancers of two KRAS G12C-targeting drugs, sotorasib and adagrasib." (PMID 37761010, 2023). "We, thus, studied the mechanism of HDAC inhibitor ITF2357 in resistance of mutant (mut)-KRAS non-small cell lung cancer (NSCLC) to pemetrexed (Pem)." (PMID 36793108, 2023). "The gene encoding KRAS is the most mutated oncogene in many cancers including pancreatic ductal adenocarcinoma (PDAC), non-small-cell lung cancer (NSCLC), and colorectal cancer (CRC)." (PMID 37686149, 2023). "SHP2 was also identified as a key factor that promotes MEK/ERK pathway activation and therapy resistance in ALK and KRAS mutant non-small-cell lung cancers (NSCLC)." (PMID 37294349, 2023). "Ongoing studies on the molecular profile of cancer have revealed that EGFR and KRAS play a role in the development, invasiveness, and metastasis of non-small cell lung cancer." (PMID 37508774, 2023). "NHTD treatment causes KRAS delocalization and showed significant anti-tumor activity in KRAS-driven non-small cell lung cancer (NSCLC) xenografts with good tolerance." (PMID 37221195, 2023). "The potential clinical use of trtDNA was mainly investigated in patients with non- small- cell lung cancer (NSCLC), testing for alterations in EGFR, including the T790M mutation and KRAS." (PMID 37542343, 2023). "Recently, sotorasib, a KRAS inhibitor against KRAS p.G12C, has emerged with promising results in pretreated non-small cell lung cancer, with an ORR of 37.1% and DCR of 80.6%." (PMID 36765821, 2023). "In mouse models of non-small cell lung cancer (NSCLC) driven by oncogenic KRAS or EGFR, LDHA was essential for CSC survival and proliferation." (PMID 37190033, 2023). "This phase II trial evaluated the safety and activity of the MEK inhibitor binimetinib combined with hydroxychloroquine (HCQ) in patients with advanced KRAS-mutant non-small cell lung cancer (NSCLC)." (PMID 37186063, 2023). "This review describes the mechanisms of targeted-drug resistance and newly identified non-small cell lung cancer targets (e.g., KRAS G12C, NGRs, DDRs, CLIP1-LTK, PELP1, STK11/LKB1, NFE2L2/KEAP1, RICTOR, PTEN, RASGRF1, LINE-1, and SphK1)." (PMID 36909198, 2023). "In contrast to non-small cell lung cancers, where KRAS G12C is most common, KRAS G12D and G12V are the two most common patterns in CRC." (PMID 37886935, 2023). "Sotorasib was developed by Amgen and approved by the FDA in 2021 for the treatment of KRAS-G12C-mutant non-small cell lung cancer." (PMID 37190303, 2023). "Somatic mutations in SMARCA4 and/or BRG1 (Brahma-related gene 1) loss are present in a subset of non-small cell lung carcinomas with distinct morphological features, harboring less EGFR mutations, but more KRAS, STK11, and KEAP1 mutations." (PMID 36371186, 2022). "Recently, it has been demonstrated that combined MEK/BET inhibitors are much more effective depending on some biomarker in triple-negative breast cancer (TNBC) and in KRAS mutant non-small cell lung cancer (NSCLC)." (PMID 35468095, 2022). "Soon after, frequent KRAS G12 mutations were confirmed in various human cancers including pancreatic ductal adenocarcinoma (PDAC), colorectal cancer (CRC) and non-small cell lung cancer (NSCLC)." (PMID 35966590, 2022).